SOCS5 (suppressor of cytokine signaling 5)
Description:
SOCS family proteins form part of a classical negative feedback system that regulates cytokine signal transduction. May be a substrate-recognition component of a SCF-like ECS (Elongin BC-CUL2/5-SOCS-box protein) E3 ubiquitin-protein ligase complex which mediates the ubiquitination and subsequent proteasomal degradation of target proteins. Inhibits for instance EGF signaling by mediating the degradation of the EGF receptor/EGFR. Involved in the regulation of T-helper cell differentiation by inhibiting of the IL4 signaling pathway which promotes differentiation into the Th2 phenotype. Can also partially inhibit IL6 and LIF signaling.
Synonyms: SOCS-5; CIS6; CISH5; CISH6; KIAA0671
Tractability: Antibody: the Human Protein Atlas places it where antibodies can reach. PROTAC: ubiquitination databases record sites on it.
Gene: Protein-coding gene on chromosome 2 (46,698,423 to 46,780,245, forward strand). Ensembl gene ENSG00000171150.
Subcellular location (Human Protein Atlas): Cytosol; Nucleoplasm; Plasma membrane
Pathways (Reactome):
Immune System: Interleukin-4 and Interleukin-13 signaling
Metabolism of proteins: Neddylation
Gene Ontology:
Molecular function: protein binding; receptor tyrosine kinase binding; epidermal growth factor receptor binding
Biological process: negative regulation of epidermal growth factor-activated receptor activity; positive regulation of proteasomal ubiquitin-dependent protein catabolic process; cytokine-mediated signaling pathway; negative regulation of signal transduction; negative regulation of T-helper 2 cell differentiation; positive regulation of T-helper 1 cell differentiation; cell surface receptor signaling pathway via JAK-STAT; cellular response to low-density lipoprotein particle stimulus; epidermal growth factor receptor signaling pathway; intracellular signal transduction; negative regulation of inflammatory response; negative regulation of interleukin-6 production; negative regulation of monocyte chemotactic protein-1 production; protein ubiquitination; vascular endothelial cell response to fluid shear stress
Cellular component: cytosol
Genetic constraint (gnomAD): Loss-of-function variants: 32 observed, 43.88 expected, observed/expected ratio (o/e) 0.73, 90% interval 0.55 to 0.98. The upper end of that interval is the gene's LOEUF score, 0.98, which puts it in group 4 of 6, group 1 being the genes least tolerant of losing a copy. Missense variants: 627 observed, 677.85 expected, observed/expected ratio (o/e) 0.92, 90% interval 0.87 to 0.99. Synonymous variants: 283 observed, 239.63 expected, observed/expected ratio (o/e) 1.18, 90% interval 1.07 to 1.3.
Homologues: Orthologues: chimpanzee SOCS5 (100% identical), macaque SOCS5 (99% identical), dog SOCS5 (98% identical), pig SOCS5 (97% identical), guinea pig SOCS5 (96% identical), rat Socs5 (95% identical), mouse Socs5 (94% identical), tropical clawed frog socs5 (81% identical), Drosophila melanogaster Socs36E (33% identical), Drosophila melanogaster Socs44A (14% identical), zebrafish socs1b (9% identical). Paralogues in human: SOCS4 (43% identical), SOCS6 (20% identical), SOCS7 (18% identical), CISH (12% identical), SOCS2 (10% identical), SOCS1 (9% identical), SOCS3 (8% identical).
Diseases named in the same sentence as SOCS5 in open-access papers:
SOCS5 is named in the same sentence as 68 diseases in open-access papers, as found by Europe PMC text mining. Sharing a sentence is not in itself a finding about the gene and the disease. The quoted sentences say what the papers report.
hepatocellular carcinoma (13 papers, 2019 to 2025). A malignant tumor that arises from hepatocytes. "DHRS4-AS1 suppresses cell proliferation and promotes apoptosis via the miR-522-3p/SOCS5 axis In hepatocellular carcinoma." (PMID 38041141, 2023). "The inhibition of suppressor of cytokine signaling-5 (SOCS5) protein can augment autophagy by activating PI3K/AKT/mTOR axis but reduce hepatocellular carcinoma metastatic potential." (PMID 37355631, 2023). "We studied the role of SOCS5 in hypoxia-induced invasion and metastasis of hepatocellular carcinoma in vitro and in vivo experiments." (PMID 36319626, 2022). "SOCS5 inhibition induces autophagy to impair metastasis in hepatocellular carcinoma cells via the PI3K/Akt/mTOR pathway." (PMID 34128694, 2021). "DHRS4-AS1 could be detected through the DHRS4-AS1/miR-522-5p/SOCS5 axis on cell proliferation, apoptosis, and cell cycle in hepatocellular carcinoma, which in turn regulates the development of hepatocellular carcinoma." (PMID 38339157, 2024). "Pro-malignant roles for SOCS5 were also observed in hepatocellular carcinoma as well, where SOCS5 inhibition induced autophagy and compromised lung metastasis of HCC cells, and where high SOCS5 levels were prognostic of poor patient outcome." (PMID 34059683, 2021). "Recently, SOCS5 has been reported over-expressed in hepatocellular carcinoma (HCC) tissues, and was correlated with poor prognosis of HCC patients." (PMID 33758600, 2021). "In hepatocellular carcinoma (HCC), controversial tumor-promoting and tumor-suppressive roles of SOCS5 have been reported." (PMID 31406106, 2019).
pancreatic cancer (11 papers, 2020 to 2023). "MiR-301a is highly expressed in human pancreatic cancer patients, which can target SOCS5 to activate JAK/STAT3 and promote the migration and invasion of pancreatic cancer cells." (PMID 36291659, 2022). "SOCS5 has been recognized as a target of miR-301a, because miR-301a inhibited the SOCS5 expression, leading to induction of JAK/STAT3 signaling, and was linked to poor survival of pancreatic cancer patients." (PMID 34095461, 2021). "SOCS5 was also commonly found to be tumor-suppressed and significantly reduced in tumors, such as non-small cell lung cancer, pancreatic cancer and also liver cancer." (PMID 34666613, 2021). "Consistent with our study, downregulation and inhibitory effect of SOCS5 have been found in breast and pancreatic cancer." (PMID 32844573, 2020). "Similarly, another research study revealed that SOCS5 partakes in impairing the invasive and metastatic capacity of pancreatic cancer via JAK/STAT3 pathway." (PMID 34666613, 2021). "A recent study showed that SOCS5 was a direct target of miR-675–3p, which activated PI3K signaling to maintain pancreatic cancer cell stemness." (PMID 33935775, 2021). "Herein, the H19/miR-675-3p/SOCS5/STAT3 axis plays an important role in pancreatic cancer cells, which revealed potential targets for the treatment of pancreatic cancer." (PMID 34977037, 2021). "As miR-302a-3p directly targets SOCS5 to boost STAT3 phosphorylation and induce the transcription of STAT3 target genes, SMARCA2 starts the miR-302a-3p/SOCS5/STAT3 signaling axis and thus potentiates pancreatic cancer metastasis." (PMID 37175555, 2023). "Furthermore, miR-301a was found to suppress the expression of SOCS5, which leads to JAK/STAT3 activation and is related to poor overall survival of pancreatic cancer patients." (PMID 35740894, 2022). "LncRNA H19 is significantly upregulated in pancreatic cancer cell lines and facilitates pancreatic cancer metastasis and EMT by directly targeting miR-675-3p, which binds to SOCS5, a member of the SOCS protein family that negatively regulates JAK2/STAT3 signaling." (PMID 35819532, 2022).
liver cancer (8 papers, 2019 to 2024). An epithelial or non-epithelial malignant neoplasm that arises from the liver. "Reportedly, via regulating the PI3K/AKT pathway, PHLDA2 affects EMT and autophagy, and inhibits the growth of colon cancer, and SOCS5 regulates autophagy pathway and promotes the transfer of liver cancer cells." (PMID 39428922, 2024). "By sponging miR-3118, lncRNA HAND2-AS1 enhances the JAK-STAT pathway, thereby promoting SOCS5 to inhibit the liver cancer cell's growth and migration." (PMID 36052283, 2022). "Recent years have seen much effect on the specific function of SOCS5 in cancers, including liver cancer, glioma, chronic lymphocytic leukemia, and breast cancer." (PMID 34666613, 2021). "In liver cancer, upregulation of miR-18a and miR-25 inhibited the expression of SOCS5, which was identified as a bona fide target of both miRNAs." (PMID 33935775, 2021). "Downregulation of SOCS5 has been detected in prostate and liver cancers." (PMID 32844573, 2020). "SOCS1 alterations through SOCS7 and CISH alterations were detected in liver cancer tissues at the following frequencies: SOCS1, 1.1%; SOCS2, 0.8%; SOCS3, 6%; SOCS4, 0.3%; SOCS5, 1.3%; SOCS6, 1.3%; SOCS7, 2.4%; and CISH, 2.7%." (PMID 39307915, 2024). "More importantly, our data suggest that the development of a SOCS5-specific inhibitor, an indirect inhibitor of HIF-1α, may be effective in controlling Pringle maneuver-induced tumor micrometastases during liver cancer resection." (PMID 36319626, 2022).
viral infection (8 papers, 2016 to 2023). "The functional mechanism of miR-221-3p and SOCS5 in immune response and viral infection still requires further investigation." (PMID 32373087, 2020). "We highlight a novel role for SOCS5 in the regulation of PI3K signaling and demonstrate that SOCS5 primarily protects against viral infection by inhibiting EGFR activity." (PMID 28195529, 2017). "This may indicate that SOCS5 is necessary to activate NF-κB during viral infection and mount a protective response." (PMID 32038638, 2019). "We next sought to test the hypothesis that SOCS5 might be regulating viral infection via negative regulation of EGFR and/or PI3K signaling." (PMID 28195529, 2017). "At low levels of virus (MOI 1.25 and 2.5), there was a higher percentage of infected Socs5−/− mAECs in comparison to wild-type cells, suggesting that Socs5−/− mAECs may be more permissive for viral infection." (PMID 28195529, 2017). "However, the role of SOCS5 has not been well understood during viral infection." (PMID 27282499, 2016). "To determine the role of JAK-STAT pathway in viral infection, we first knocked down the expression of STAT5B and SOCS5 using RNAi in viruliferous SBPHs." (PMID 36928081, 2023). "Using a mouse model of encephalitis, we demonstrate that lack of SOCS5 results in changes in the pathogenesis and clinical outcome of a neurotropic virus infection." (PMID 36366574, 2022). "The role of SOCS5 has not been well identified during viral infection." (PMID 30841905, 2019). "Thus there is a unique role for SOCS5 in regulating viral activation of the EGFR in lung epithelial cells and this study confirms an important role for endogenous EGFR activity in facilitating viral infections." (PMID 28195529, 2017). "In addition, no obvious effect on protein level accumulation of BCL2 was detected after treating nonviruliferous SBPH with dsSOCS5 compared with the control (lanes 1 vs. 2), suggesting that SOCS5 imposes a negative effect on BCL2 accumulation during viral infection." (PMID 36928081, 2023). "Finally, we have shown in vivo and in primary human cells, that SOCS5 acts to negatively regulate EGFR and PI3K signaling and while both are important positive mediators of influenza virus infection, it is SOCS5 restriction of EGFR activity, which limits viral infection in lung epithelium." (PMID 28195529, 2017). "However, the function of SOCS5 has not been well studied with respect to the viral infections." (PMID 27282499, 2016). "Next, after RSV crude extracts were injected into the hemolymph of nonviruliferous SBPHs, the protein levels of SOCS5 and phosphorylated STAT5B gradually increased during the course of viral infection." (PMID 36928081, 2023).
breast carcinoma (7 papers, 2014 to 2023). "Furthermore, high expression levels of LINC01119 and SOCS5 associated with shorter relapse-free survival (RFS) in breast cancer patients in general and poorer overall survival (OS) in those diagnosed with BLBC in particular." (PMID 34059683, 2021). "We show that LINC01119 and SOCS5 exhibit tight correlation across multiple breast cancer gene sets and that they are highly enriched in TNBC patient cohorts." (PMID 34059683, 2021). "The extent to which this pathway operates identically in additional breast cancer subtypes (or other cancers altogether) will necessitate the detailed determination of cellular SOCS5 targets, partners, and mechanism-of-action in a context-dependent fashion." (PMID 34059683, 2021). "We found that SOCS5 positively correlated with LINC01119 across multiple different clinical breast cancer datasets, which included GSE28844, GSE16446, GSE102484, and GSE12276." (PMID 34059683, 2021). "For example, EVs derived from breast cancer cells containing miR-9 effectively decreased suppressor of cytokine signaling 5 (SOCS5) expression in HUVECs." (PMID 33363175, 2020). "Other studies showed that miR151 inhibited cell proliferation, tumor growth, and invasion by down-regulating the suppressor of cytokine signaling 5 (SOCS5) or TWIST1 in breast cancer cells, or leading to the suppression of PI3K/AKT phosphorylation in prostate cancer cells." (PMID 37582765, 2023). "Additionally, Kaplan–Meier plot analysis revealed an association between high Linc01119 and SOCS5 expression levels and shorter RFS in breast cancer patients." (PMID 36139687, 2022). "We evaluated expression of SOCS1–3 and SOCS5 genes in breast cancer samples compared with the corresponding adjacent non-cancerous tissues (ANCTs)." (PMID 30453988, 2018). "In addition, LINC01119 and SOCS5 expression were significantly enriched in several TNBC patient cohorts and exhibited substantial and tight correlation with one another across multiple breast cancer gene sets." (PMID 34059683, 2021).
cervical cancer (7 papers, 2015 to 2024). A primary or metastatic malignant neoplasm involving the cervix. "In the case of cervical cancer and human endothelial cells, hsa-miR-9-5p has been observed to promote angiogenesis by targeting SOCS5 and CXCR4, respectively." (PMID 38628314, 2024). "Later, in 2015, Kim’s group analyzed SOCS1, SOCS3, and SOCS5 in cervical cancer samples and HPV+ cervical cancer cell lines; they found that the expression of these three SOCS proteins decreased compared to tissues from the normal cervix." (PMID 37372319, 2023). "For example, miR-9-5p can target PAK4 to repress the proliferation and inhibit the apoptosis of colon cancer cells; in cervical cancer, miR-9-5p can regulate the angiogenesis and radiosensitivity of cervical cancer cells by targeting SOCS5." (PMID 33776787, 2021). "For instance, miR-9-5p could suppress tumor proliferation and migration in gastric cancer by targeting neuropilin-1, but it acted as an oncogene promoting angiogenesis and invasion by inhibiting SOCS5 in cervical cancer." (PMID 35179718, 2022). "SOCS5 was also identified as the target of miR-9-5p in cervical cancer cells." (PMID 33935775, 2021). "All these results led to the conclusion that SOCS1, SOCS3, and SOCS5 expression ishigher in normal tissue than in cervical cancer, and support the possibility that downregulation of SOCS might contribute to the tumorigenesis or maintenance of cervical cancer." (PMID 25849377, 2015). "SOCS5 was hardly detected in cancer cells, including ESCC (CE81T and KYSE-70), A549 (lung cancer), ECV304 (bladder cancer), and HeLa (cervical cancer) cells." (PMID 33758600, 2021). "SOCS1, SOCS3, and SOCS5 expression was lower in cervix cancer than surrounding normal tissue, and the mRNA levels of SOCS genes were lower in cervical cancer cell lines than in normal cervix tissue or fibroblast cell lines." (PMID 25849377, 2015). "All cervical cancer cell lines tested showed lower expression of SOCS1, SOCS3, and SOCS5 than normal tissue or cell lines." (PMID 25849377, 2015). "In contrast, no DNA methylation was detected in the SOCS3 and SOCS5 promoter region, at least in the CpG-enriched region examined in this experiment, of all cervix cancer cell lines." (PMID 25849377, 2015). "Wild-type cervical cancer cell lines showed repressed expression of SOCS1, SOCS3, and SOCS5." (PMID 25849377, 2015). "In contrast, SOCS5 gene expression was not changed at all by HDAC inhibition in WI-38 or in any of the cervical cancer cells tested." (PMID 25849377, 2015).
asthma (6 papers, 2008 to 2023). "While little is known about the function of SOCS-5, it has been shown to be involved in a variety of allergic disease states such as AD and asthma." (PMID 37511138, 2023). "Further, astragalin significantly increased SOCS5 expression in ovalbumin (OVA)-induced allergic inflammation in the murine asthma model, as SOCS5 is known to prominently reduce Th2 differentiation by inhibiting IL-4 signaling." (PMID 35889539, 2022). "SOCS5 has been shown to be involved in a variety of allergic disease states, including AD and asthma." (PMID 35889539, 2022). "Airway hyperresponsiveness in the asthma model of SOCS-5 transgenic was also enhanced compared to wild-type mice." (PMID 18315837, 2008). "Expressions of SOCS3 and SOCS5 mRNA were analyzed by real-time quantitative PCR in peripheral CD4 T cells from adult patients with NAEB, asthma and healthy controls." (PMID 21765854, 2011).